STAT3 (signal transducer and activator of transcription 3)
Diseases named in the same sentence as STAT3 in open-access papers (continued):
Sharing a sentence is not in itself a finding about the gene and the disease.
cancer (continued). "Another important study investigating the possible effect of Stat3 on immune suppression of cancer cells found that the inhibition of Stat3 with antisense oligonucleotide and with dominant-negative form of Stat3 (Stat3β) resulted in an increase in IL-6 in mouse cancer cells." (PMID 21122157, 2010). "Besides, STAT3 regulates human telomerase reverse transcriptase (hTERT) expression in human cancer and primary cells." (PMID 20576128, 2010). "Because the IL-6 feed-forward loop plays important role in the pathogenesis of inflammation-induced cancer as well as the drug resistance of cancer cells, the regulation of Stat3 could potentially be used to suppress IL-6 autocrine production in cancer cells." (PMID 21122157, 2010). "Our knock-down studies of AS2, MCF-7/ADR, and KC-CPT100 cells and our pharmacological inhibition experiments with seven established cell lines and 20 clinical samples revealed that Stat3 did in fact affect expression of IL-6 in most of the cancer cells we tested." (PMID 21122157, 2010). "STAT3 has therefore been considered as a potential therapeutic target for cancer treatment." (PMID 20461084, 2010). "Interestingly, some of the HPV16+ precancers and cancer cases particularly the lesions with WDSCC histopathology showed a lower level of STAT3/pSTAT3 expression and nuclear positivity." (PMID 20977777, 2010). "Both HIF-1 production and Stat3 activity are upregulated in many types of cancer." (PMID 20204067, 2010). "Our findings suggest that Stat3 could potentially be regulated to suppress IL-6 autocrine production in cancer cells to inhibit the progression of cancer and reduce drug resistance." (PMID 21122157, 2010). "Similarly, AG490 treatment also decreased the IL-6 secretion in various drug resistant cancer cells exhibiting constitutively active Stat3." (PMID 21122157, 2010). "Thus, STAT3 and Smad3 sequential activities in the cancer cells depended on IL-6 and TGF-β secreted in the supernatant and required NF-κB activity." (PMID 20520770, 2010). "Overactivation of STAT3 has been identified in many cancers." (PMID 19759907, 2009). "STAT3 has well established roles in cell proliferation, growth and survival, and its persistent activation has been detected with high frequency in many human cancers." (PMID 19712481, 2009). "STAT3 is focusing more and more interest in cancer therapy as it is often overactivated in cancer." (PMID 19455144, 2009). "Furthermore, the expression of constitutively-active STAT3 has been observed in various types of human cancer including multiple myeloma, colon, ovary, liver, lung, head, and neck cancers." (PMID 19730699, 2009). "Inhibition of the STAT3 pathway thus represents an attractive therapeutic approach for cancer." (PMID 19127268, 2009). "LLL-3, a structural analogue of STA-21 with a smaller molecular weight and the added benefit of being easier to synthesise, may be a more suitable agent for targeting cancer cells with constitutively activated STAT3 pathway." (PMID 19127268, 2009). "Some recent studies have implicated a role of STAT3 and EGFR in mediating EMT in cancer cells." (PMID 19088723, 2009). "Since an apoptosis inhibitor survivin is a transcriptional target of STAT3 and one of validated cancer therapeutic target, we investigated whether the expression of survivin in DU145 cells was affected by glucosamine." (PMID 19744341, 2009). "In addition, STAT-Finder identified novel STAT3 target genes among a group of genes that are over-expressed in human cancer cells." (PMID 19730699, 2009). "With regard to the apoptotic effect of the combination therapy, it is reported that Wnt/β-catenin signalling is closely linked to JAK–STAT signalling, and regulates STAT3 expression, thus enhancing cell growth and anti-apoptotic activity of various cancer cells." (PMID 19401692, 2009).
cancer (continued). "In addition to IL-6, the expression of cyclin D1, c-myc, survivin, Bcl2, Mcl1, and VEGF, all of which are regulated by Stat3 activity, and play a crucial role in apoptosis and progression of cancer, are also down regulated in response to avicin D." (PMID 19440292, 2009). "Furthermore, it was found that genistein inhibits cancer cells through modulating the expression of certain transcription factors, such as STAT-3, Nrf1, Nrf2, AP-1 and CREB." (PMID 19742137, 2009). "Given the prevalence of STAT3 dysregulation in cancer, its role in promoting cell cycle progression, cellular transformation, and prevention of apoptosis, and its unique position downstream of multiple activating tyrosine kinases, STAT3 represents a potential target for therapeutic intervention." (PMID 19284568, 2009). "Previously identified compounds that target Stat3 induce cancer cell apoptosis." (PMID 19274102, 2009). "Consequently, the inhibition of STAT3 by a variety of means has been demonstrated to exert a potent anti-cancer effect." (PMID 19712481, 2009). "Thus, Stat3 has been identified as a potentially high-yield target for drug development to treat many cancers." (PMID 19274102, 2009). "This suggests that JNK and STAT-3 may constitute a universal signaling pathway to mediate adiponectin's pathophysiological effects on metabolic syndrome and the pathogenesis of cancer." (PMID 20030801, 2009). "STAT3 has therefore drawn attention as a novel target for cancer therapy." (PMID 18651980, 2008). "Hence, we now provide evidence for another mechanism for impairing HIF-1α function in cancer cells by 2ME2-like inhibitors in terms of diminishing STAT3 activation." (PMID 18651980, 2008). "Stat3 is also involved in the initiation and promotion of cancers and angiogenesis." (PMID 17598902, 2007). "In addition, inhibition of the activation of Stat3 blocked the proliferation and survival of those cancer cells." (PMID 17925034, 2007). "Activated STATs (particularly STAT3) are found in a range of cancers." (PMID 17295906, 2007). "The constitutive activation of Stat3 is frequently detected in a variety of human cancers." (PMID 17311011, 2007). "However, in numerous cancer-derived cell lines and in an ever-growing number of primary tumors, Stat proteins (in particular, Stat3) are persistently tyrosine-phosphorylated." (PMID 17531096, 2007). "Persistently, activation of Stat3 has become an attractive cancer therapy target." (PMID 17598902, 2007). "Moreover, STAT3 phosphorylation by EGF or IL-6 was diminished in multiple CARP-1 null cancer cells." (PMID 42121855, 2026). "Targeting STAT3 in combination with chemotherapeutic or immunotherapeutic drugs, may improve cancer treatment outcomes by suppressing cell proliferation and sensitising cancer cells to death." (PMID 39985075, 2025). "Notably, LIF‐induced STAT3 signaling also participates in HCC development, exemplified by arsenic trioxide, which simultaneously suppresses the LIF/JAK1/STAT3 and NF‐kB signaling pathways, thereby promoting cancer stem cell differentiation and impeding HCC development." (PMID 40416597, 2025). "Consequently, inhibiting STAT3's activity presents a strategic approach to disrupt these oncogenic pathways and enhance therapeutic efficacy, making it a focal point for developing novel cancer treatments." (PMID 40918170, 2025). "Notably, PLTs have achieved extensive application in the treatment of cancer and inflammatory disorders via modulating key signaling pathways, including NF-κB, STAT3, and MAPK, which are essential to both oncogenic progression and the regulation of immune responses." (PMID 40051564, 2025). "By comparison, CPT is particularly prominent in cancer and fibrosis research, where it produces sustained STAT3 suppression with downstream network inhibition, interferes with metabolic–inflammatory coupling and cell-cycle progression, and is widely regarded as a STAT3-oriented lead." (PMID 41011209, 2025).
cancer (continued). "Therefore, inhibition of STAT3 not only inhibits the growth of cancer cells but also may increase the anticancer immune response." (PMID 40729003, 2025). "Out of the STAT3 inhibitors, silibinin has been shown to have specific anti-inflammatory, antioxidant, antiproliferative, antimetastatic and anti-angiogenic action, and thus, it could have interesting antitumor activity against several types of cancers." (PMID 41441207, 2025). "TAMs are actively recruited and conditioned by the tumor: cancer cells and stromal cells, like cancer-associated fibroblasts, secrete CCL2 and colony stimulating factors that recruit monocytes and induce their differentiation into MDSCs and M2 TAMs via STAT3-activating cytokines (IL-6, etc.)." (PMID 40227782, 2025). "Furthermore, it was observed that a STAT3 inhibitor could sensitize HeLa cancer cells to apoptosis induced by cationic amphiphilic antihistamines." (PMID 39886963, 2025). "Therefore, inhibiting STAT3 could provide multifaceted benefits by disrupting these cancer-supportive mechanisms simultaneously." (PMID 40075607, 2025). "Moreover, in a mice model, NLRP3 deletion inhibited lung tumorigenesis by reducing the levels of IL-1β, whereas its activation upregulated signaling pathways like PI3K-AKT, Erk1/2, and STAT3, which altogether contributed to increased proliferation and cancer metastasis." (PMID 41376623, 2025). "However, recent studies suggest that PI3K may enhance STAT3 phosphorylation through TEC kinase in certain cancer cells." (PMID 40795247, 2025). "Consequently, the JAK2/STAT3 axis emerges as a rational therapeutic target for cancer." (PMID 40309242, 2025). "Given that both MDM2 and STAT3 inhibitors have demonstrated promise in preclinical cancer studies, including those involving other hematologic malignancies, combined targeting of these two pathways may offer a more effective and safer treatment approach for ALL." (PMID 40943567, 2025). "Furthermore, STAT3 mediated regulation of glucose metabolism in types of cancer." (PMID 40697388, 2025). "Since interleukin-6/STAT3 signaling is known to stimulate prominin-1 expression, prominosome-mediated cancer cell–macrophage communication could create a positive feedback loop that further enhances cancer growth and metastasis." (PMID 39881297, 2025). "Moreover, STAT3 plays a crucial role in the G1 to S phase cell cycle transition by modulating the expression of cyclins D1, D2, D3, A, and Cdc25A, while concurrently regulating p21 and p27, thereby influencing cancer-related activities." (PMID 40444012, 2025). "Therefore, STAT3 activation in these cancer cells might help them prevent apoptosis and enhance self-renewal." (PMID 40149331, 2025). "Additionally, growing evidence has underscored that targeting STAT3 could effectively overcome Cisplatin resistance in various types of cancer cells." (PMID 39997178, 2025). "Thus, the STAT3 pathway is considered a promising target for cancer treatment." (PMID 40408503, 2025). "Additionally, DDSs integrated with anti‐STAT3 inhibitors have demonstrated superior outcomes in cancer treatment compared with the use of inhibitors alone, highlighting the potential of NP‐based approaches to enhance drug targeting, reduce systemic toxicity, and improve overall therapeutic efficacy." (PMID 40166646, 2025). "Thus, especially in cancer types with hyperactive NF-kB, it may be necessary to fully remove STAT3 in order to combat the U-STAT3 oncogenic pathways." (PMID 40075607, 2025). "The ablation of key autophagy or lysosome-dependent cell death effectors, such as STAT3 and cathepsin B, could inhibit ferroptotic cancer cell death, whereas the knockout of SLC7A11 or GPX4 could reduce autophagy, thereby providing further protection against ferroptosis induced by Golgi stress." (PMID 41462678, 2025). "Therefore, STAT3 has been recognized as an attractive potential therapeutic target in cancer." (PMID 40118821, 2025).
cancer (continued). "Therefore, exploring novel strategies for targeting STAT3 in cancer therapy remains a priority." (PMID 40166646, 2025). "Several key signaling pathways, including the mammalian target of rapamycin, Wnt, STAT3, mitogen‐activated protein kinase (MAPK), and phosphoinositide 3‐kinase, play essential roles in cell growth, survival, and proliferation, and their dysregulation is a hallmark of cancer." (PMID 40166646, 2025). "Consequently, CEBPB may play a pivotal role in the “inflammation-cancer” nexus by modulating the NF-κB/STAT3 signaling pathway." (PMID 40487290, 2025). "Moreover, luteolin effectively limits the expression levels of many proteins including extracellular signal‐regulated kinase (phosphorylated (p)‐Erk1/2), epidermal growth factor receptors, (p‐EGFR and p‐Akt), and activator of transcription and signal transducer (p‐STAT3) in cancer cells." (PMID 39830909, 2025). "Thus, IL-6-targeted therapies that inhibit STAT3 activity could still be effective against cancer cells chronically exposed to IL-1." (PMID 41374981, 2025). "Similarly, STAT3—a central mediator of cytokine signaling—was upregulated, highlighting its contribution to cellular processes such as proliferation, resistance to apoptosis, and angiogenesis, all of which are features of cancer." (PMID 41154628, 2025). "In prostate cancer, ARPC1A is transcriptionally regulated by STAT3: It not only supplies energy to cancer cells by enhancing oxidative phosphorylation but also maintains an immunosuppressive microenvironment by inhibiting ferroptosis—creating favorable conditions for cancer progression." (PMID 41332982, 2025). "Notably, STAT3 is integral to both inflammation and cancer progression, as its persistent activation is frequently observed in various malignancies, where it drives tumorigenesis by promoting cell proliferation, inhibiting apoptosis, and facilitating angiogenesis." (PMID 40704145, 2025). "One such combination is the deformable cationic liposome with curcumin and STAT3 siRNA, where the synergistic effect between an anti-inflammatory/antioxidant agent and an oncogenic transcription factor was particularly noteworthy, targeting inflammation and cancer progression." (PMID 39339235, 2024). "Moreover, the endoplasmic reticulum of macrophages can be induced by lipids in cancer cells to induce stress and activate STAT3 and X-box binding protein 1 (XBP1) through inositol-requiring enzyme 1 (IRE1) splicing, thus promoting the pretumor phenotype of TAMs." (PMID 39192979, 2024). "Thus, the inhibitory effect of BSN on cancer cachexia could be mediated through modulation of the STAT3 pathway." (PMID 38807976, 2024). "While an oncogenic transcription factor such as STAT3 or STAT5 may regulate genes that underlie a cancer phenotype, interrupting these pathways may not be sufficient to kill established tumors." (PMID 38611065, 2024). "In addition to EZH2, STAT3 has also been found to be hyperactive in numerous cancers." (PMID 39204206, 2024). "Although most research into STAT3 activation and downstream signalling has mainly been studied in the context of IL-6 stimulation, recent studies have shown an important role for IL-11 in STAT3 activation, especially in the initiation and progression of cancer." (PMID 38248304, 2024). "However JAK activation alone cannot explain the level of STAT3 activation observed in cancer." (PMID 38760429, 2024). "In studies of human cancers, CD44 is associated with STAT3, which may lead to STAT3 activation." (PMID 38247821, 2024). "Therefore, STAT3 has become a promising therapeutic target in a wide range of cancers." (PMID 38245798, 2024).
cancer (continued). "Apart from providing more energy, there are also reports that FAO might protect cancer cells from chemotherapy-induced apoptosis by increasing the lipid synthesis on the mitochondrial membrane, or maintaining the cancer cell stemness via the CD96-Src-Stat3 signalling pathway." (PMID 38582885, 2024). "These efforts may provide new perspectives for STAT3-based target therapy in cancer." (PMID 38245798, 2024). "Moreover, NCAPG2 could promote PCa malignancy and drive cancer stemness through a previously unreported STAT3/c-MYC signaling-dependent mechanism, which provides a new direction for targeted PCa therapy." (PMID 38166947, 2024). "Thus, this positive activation loop may be important for accelerating and maintaining STAT3 activity in cancer cells." (PMID 38760429, 2024). "Therefore, anticancer therapeutic strategies that inhibit both PI3K/Akt and STAT3, particularly in PTEN-deficient cancers, could be more effective in halting tumorigenesis." (PMID 38785562, 2024). "Furthermore, STAT3 has been identified as a crucial factor in inflammation‐related cancers." (PMID 38807976, 2024). "Additionally, STAT3 expression was correlated with cancer progression." (PMID 39840049, 2024). "Interestingly, STAT3 mRNA expression was higher in LM4 cancer cells than in Pa cancer cells." (PMID 39126553, 2024). "Then we examined whether STAT3 activation phenocopies the cancer cell-derived collagen effects." (PMID 38907027, 2024). "In addition to targeting PI3K/Akt in cancer, the signal transducer and activator of the transcription 3 (STAT3) pathway counterbalances PI3K/Akt/mTOR signalling via PTEN and promotes tumourigenic proliferation, invasion, migration, and angiogenesis in most cancers." (PMID 38785562, 2024). "Moreover, STAT3 plays a crucial role in regulating the EMT process in several cancer types." (PMID 39085755, 2024). "Based on recent experimental studies, showing PTPRM knockdown or induced PTPRM methylation to increase STAT3 phosphorylation in cancer cells, we hypothesized PTPRM hemizygosity as a result of the interstitial 18p deletion in the triplets to cause increased STAT3 phosphorylation in immune cells." (PMID 39359478, 2024). "The focal adhesion kinase (FAK), a consequential downstream constituent of STAT3, exhibited a marked presence in invasive cancer cells, exemplified by RT-4 in our experimental condition, was studied to explore the potential synergistic effects emanating from the perspective of the STAT3 pathway." (PMID 38886756, 2024). "Persistent STAT3 activation occurs when there is hyperactivation in the upstream signalling cascade or defective downstream regulation, thus resulting in upregulation of several major oncogenic signalling pathways and contributing to tumorigenesis of multiple cancers, including GBM." (PMID 38615034, 2024). "Therefore, finding an inhibitor of STAT3 might be a promising approach in prevention and targeted therapy of cancer." (PMID 38310190, 2024). "Also, some studies have shown that CD44 and STAT3 cooperate with each other in cancer promotion." (PMID 38385088, 2024). "Moreover, IL-6/JAK/STAT3 signaling up-regulates downstream target genes with anti-apoptotic and proliferative effects, promotes plasticity, invasion, and metastasis of cancer cells and angiogenesis, and induces cancer resistance." (PMID 37507626, 2024). "Moreover, the interaction between p-STAT3 and Ack-STAT3 can impact cancer metastasis." (PMID 38560562, 2024). "Targeting the IL-6/JAK2/STAT3 signaling axis may enhance the effectiveness of cancer therapies." (PMID 39103836, 2024). "Thus, in cancer cells that are dependent on STAT3 for survival, it may be difficult for survival to be maintained by continuous activation of JAK alone." (PMID 38760429, 2024). "Thus, enhancing STAT3 ubiquitination in cancers represents a promising therapeutic strategy." (PMID 39195486, 2024). "However, STAT3 is constitutively activated in diseases like cancer." (PMID 39309691, 2024).